NCF2 (neutrophil cytosolic factor 2)
Diseases named in the same sentence as NCF2 in open-access papers (continued):
Sharing a sentence is not in itself a finding about the gene and the disease.
Sepsis (5 papers, 2012 to 2025). Sepsis is defined as life-threatening organ dysfunction caused by a dysregulated host response to infection. "Other studies, using differential gene expression and functional enrichment analyses, have identified a variety of ferroptosis-related genes linked to sepsis, such as neutrophil cytosol factor 2 (NCF2), STEAP3." (PMID 41250137, 2025). "This study identified two FR-DEGs (Ncf2 and Steap3) associated with sepsis-induced ALI via transcriptome analyses, as well as their functional and metabolic pathways." (PMID 37081490, 2023). "Despite the identification of several ferroptosis-related genes, such as NEDD4L and NCF2, through transcriptomic analyses and machine learning models, validation in independent human sepsis cohorts remains limited." (PMID 41250137, 2025). "The upregulation of NCF2 in sepsis-induced ALI was validated in independent mouse cohorts from Gene Expression Omnibus datasets GSE165226 and GSE168796, confirming elevated NCF2." (PMID 41250137, 2025). "NCF2 can serve as a biomarker related to ferroptosis in various diseases, such as Alzheimer’s disease, amyotrophic lateral sclerosis, sepsis-induced acute lung injury, and LN." (PMID 41035016, 2025). "Eventually, the genes chosen by the two models were combined to further screen diagnostic genes for sepsis-induced ALI, and three common genes (Ncf2, Steap3, and Gclc) were obtained." (PMID 37081490, 2023). "Validation results using GSE165226 showed that the expression of Ncf2 was significantly higher in sepsis-induced ALI samples, whereas the expression of Steap3 was higher in the control samples." (PMID 37081490, 2023). "Sepsis is a disease characterized by inflammatory dysfunction, and some GO terms of inflammation, including leukocyte differentiation and bacterial responses, were identified in relation to Ncf2 and Steap3." (PMID 37081490, 2023). "Thus, it is conceivable to hypothesize that Ncf2 may participate in ferroptosis and the pathological process of sepsis-induced ALI by influencing the activity of NADPH oxidase and the production of ROS; however, this needs to be proven experimentally in the future." (PMID 37081490, 2023). "In general, in the process of sepsis-induced ALI, Ncf2 and Steap3 mainly participate in disease pathways involved in infection, immunity, and inflammation." (PMID 37081490, 2023). "Our results showed that some inflammatory signal-relevant pathways were enriched by Ncf2 and Steap3, such as the JAK-STAT, MAPK, and cytokine activation signaling pathways, which have been shown to be involved in ferroptosis and sepsis-induced lung injury." (PMID 37081490, 2023). "In the study, it was found that Ncf2 expression was high in sepsis-induced ALI samples, confirming the relationship of Ncf2 dysregulation and ALI progression." (PMID 37081490, 2023). "In the GSE66099 control and sepsis groups, NCF2 (neutrophil cytosolic factor 2), NLRP12 (NLR family pyrin domain-containing 12), and NCR2 (natural cytotoxicity-triggering receptor 2) had degree 26, 26, and 34, respectively." (PMID 33667236, 2021). "The boxplot revealed 26 differentially expressed genes between the sepsis-induced ALI and control samples: Ncf2, Slc2a6, Cd44, Txnip, Slc2a1, Ubc, Hspb1, Zfp36, Arntl, Ddit4, Tnfaip3, Txnrd1, Mt1, Hmox1, Gch1, Gclc, Stat3, Egfr, Hif1a, Bach1, Socs1, Dusp1, Cdkn1a, Fth1, Steap3, and Alox12." (PMID 37081490, 2023). "Moreover, the differential expression of Ncf2 and Steap3 were verified in GSE165226, GSE168796 and qRT-PCR, which may provide a reference for the pathogenesis of sepsis-induced ALI from the perspective of bioinformatics." (PMID 37081490, 2023).
Obesity (4 papers, 2016 to 2024). Accumulation of substantial excess body fat. "Taken together, NCF2 may be a promising research target for obesity and may represent a good target gene for studying maternal obesity and fetal programming, even though further studies are imperative." (PMID 39296904, 2024). "The hub genes calculated by Cytoscape software are MNDA (score 320), CYBB (score 314), CD86 (score 312), FCGR2C (score 242), NCF2 (score 240), LCP2 (score 182), TLR8 (score 148), HLA-DRA (score 54), LCP1 (score 30), and PTPN22 (score 8), which are considered to be associated with obesity-related AF." (PMID 36671813, 2023). "The expression of PTX3, NCF2, HOXB5, ABCA6, and C1orf162 were upregulated in the placenta of mothers with obesity compared with mothers with normal BMI." (PMID 39296904, 2024). "We detected five genes were different expressed, YWHAQ, NCF2, DHRS9 and SCNA only up-regulation in PCOS-obesity patients with no significance different between control and PCOS-nonobesity patients." (PMID 27056885, 2016). "YWHAQ, NCF2, DHRS9 and SCNA were up-regulation in PCOS-obesity patients with no significance different between control and PCOS-nonobesity patients, which may be activated by lower DNA methylaiton." (PMID 27056885, 2016).
asthma (3 papers, 2016 to 2022). "Intriguingly, areas of methylation were mainly adjacent to asthma susceptibility genes and in particular genes related to fibrotic and inflammatory pathways (e.g. neutrophil cytosolic factor 2; NCF2, and MMP14)." (PMID 27658857, 2016). "The levels of most proteins (ITGAM, ITGB2, MMP12, NCF1, NCF2, NCF4, RAC2 and Vav1) were higher in the asthma condition (shown in red) than those in the control condition or after SCIT condition." (PMID 34618857, 2021).
breast carcinoma (3 papers, 2018 to 2023). "Ncf2‐deficient mice showed decreased pulmonary metastatic colonisation by EO771.LMB breast cancer cells relative to wild‐type mice." (PMID 30062795, 2018). "Besides, NCF2 was selected to construct a Macrophage‐Related Gene Prognostic Index for glioblastoma, and methylation of CpG sites of NCF2 was associated with the risk of breast cancer." (PMID 36680322, 2023).
colon cancer (3 papers, 2015 to 2025). "We performed bioinformatic analysis to assess the gene expression of NCF4, NCF1, and NCF2 in colon tumors and control tissues from 480 colorectal cancer (CRC) patients and 41 paired tumors and associated normal tissues available in the TCGA database." (PMID 38886341, 2024). "Of them, 10 aging-related CpG sites were mapped to 6 genes (i.e., TNF, BICC1, TBX3, SUCNR1, NCF2, DIP2B), and the altered methylation of cg03037030 located in TNF was associated with the risk of CRC, colon cancer, and rectal cancer, with consistent effect direction." (PMID 41197401, 2025).
colorectal cancer (3 papers, 2017 to 2024). A primary or metastatic malignant neoplasm that affects the colon or rectum. "NCF2/p67phox expression has been reported to be upregulated in clear cell renal cell carcinoma (ccRCC), urothelial carcinoma, malignant glioma, hepatocellular carcinoma and colorectal carcinoma, and associated with poor prognosis." (PMID 37612524, 2023). "Furthermore, a longer five-year survival rate for colorectal cancer patients correlated with a higher expression of NCF4, but not NCF1 or NCF2." (PMID 38886341, 2024).
glioblastoma (3 papers, 2022 to 2026). The most malignant astrocytic tumor (WHO grade IV). "Both the CGA cancer database and clinical evidence reveal that relatively high enrichment of NCF2 genes is associated with a bad outcome in glioblastoma patients." (PMID 36015199, 2022).
insulin-dependent diabetes mellitus (3 papers, 2019 to 2024). "GSEA analysis also revealed that patients with obstructive CAD with higher expression levels of NCF2, MYO1F, S1PR4, and FCN1 in PBMC showed enriched pathways in viral myocarditis, Leishmania infection, type I diabetes mellitus, and hematopoietic cell lineage." (PMID 31245869, 2019).
liver disease (3 papers, 2016 to 2021). "Moreover, treatment with CeO2NPs significantly reduced the hepatic expression of iNOS and NCF2 in this model of liver disease." (PMID 31783479, 2019).
osteomyelitis (3 papers, 2023 to 2025). An acute or chronic inflammation of the bone and its structures due to infection with pyogenic bacteria. "Notably, 3 genes (NCF2, RAC2, and MMP9) were involved in Staphylococcus aureus infection, the most prevalent etiology of osteomyelitis in diabetic foot ulcer infections." (PMID 37904457, 2023).
steatosis (3 papers, 2019 to 2023). Increased lipid within the cytoplasm of cells. "Another female mice model fed with Western diet (WD)-induced NASH increased the expression of genes, including steatosis (SFA, MUFA, MUFA-containing di- and triacylglycerol), inflammation (TNFα), oxidative stress (Ncf2), and fibrosis (Col1A) via lipidomics and transcriptomic approach." (PMID 31795276, 2019).
Stroke (3 papers, 2021 to 2022). Sudden impairment of blood flow to a part of the brain due to occlusion or rupture of an artery to the brain. "Bioinformatic analyses indicated that up-regulated expression of NCF2 increased susceptibility to unstable atherosclerotic plaque-related stroke." (PMID 33613306, 2021).
Autoimmunity (2 papers, 2019 to 2024). The occurrence of an immune reaction against the organism's own cells or tissues. "Other mutations in NCF2 have been linked to inflammatory bowel disease and autoimmunity, but without CGD, suggesting similarities in the pathogenesis." (PMID 31832070, 2019).
carotid atherosclerosis (2 papers, 2021 to 2022). A thickening and loss of elasticity of the walls of carotid arteries that occur with formation of atherosclerotic plaques. "NCF2, IQGAP2, and CD86 might play crucial roles in the process of carotid atherosclerosis." (PMID 33613306, 2021).
clear cell renal cell carcinoma (2 papers, 2021 to 2023). "In our study, NCF1, NCF2, and NCF4 showed a high expression in renal clear cell carcinoma." (PMID 34708124, 2021).
Hyperglycemia (2 papers, 2011 to 2026). An increased concentration of glucose in the blood. "Polymorphisms in CYBB (NOX2), NCF1 (p47phox), and NCF2 (p67phox) may differ from Caucasian or Asian populations, potentially modulating basal NOX2 activity and response to hyperglycemia." (PMID 41607455, 2026).
immune deficiency disorders (2 papers, 2022). "In comparisons to both healthy controls and other primary immunodeficiencies (PIDs) including NCF1/NCF2 mutant CGD, we defined the gp91 expression level in patients with X91+ as > 70%, X91− as 5–70%, and X910 as < 5%." (PMID 35796921, 2022). "Neonatal or infantile-onset IBD is often associated with primary immune deficiency disorders, especially those caused by mutations in IL-10, XIAP, NCF2, IPEX, and TTC7A." (PMID 35783276, 2022).
Miscarriage (2 papers, 2022 to 2025). A pregnancy that ends at a stage in which the fetus is incapable of surviving on its own, defined as the spontaneous loss of a fetus before the 22th week of pregnancy. "Elevated concentrations of NOX1 and NCF2 in “NETs-positive” women with miscarriage seem to indicate the increased activity of NADPH oxidase, a key enzyme involved in the initiation of NET formation." (PMID 36181646, 2022). "Further research on 17 core enriched genes expressed at the MFI indicated that CXCL11, MMP10, FOS, FOSB, LY96, and NCF2 may be closely related to miscarriage." (PMID 41232126, 2025). "The present study also showed a strong positive correlation between BPA concentration and tobacco smoking in women with miscarriage, which suggests that BPA increases the risk of pregnancy loss by activating the ROS/NETs pathway due to its concomitant correlation with NOX1 and NCF2." (PMID 36181646, 2022). "As there are no studies focusing on NOX1 and NCF2 in pregnant women or women with miscarriage in the literature, we could not compare the results obtained in this study." (PMID 36181646, 2022).
myocardial infarction (2 papers, 2021 to 2025). Gross necrosis of the myocardium, as a result of interruption of the blood supply to the area, as in coronary thrombosis. "We analyzed the expression levels of LILRB2, TLR2, NCF2, and S100A9 in AMI samples (blood samples on the first day of myocardial infarction) and stable coronary artery disease (CAD) controls." (PMID 34490057, 2021).
nasal polyps (2 papers, 2021 to 2022). "Expression levels of ALOX5AP, AQP9, CCL13, EMR3, F13A1, GAPT, and NCF2 were significantly higher in nasal polyp samples from ACRSwNP patients compared with the expression levels in samples from healthy subjects." (PMID 36059464, 2022). "Expression of NCF2 in different inflammatory cells found in nasal polyp tissues was explored using immunofluorescence staining." (PMID 36059464, 2022). "Next, we identified the protein level of the seven hub genes (ALOX5AP, BCL2A1, BTK, CYBB, NCF2, HCK, and HK3) from nasal polyps from CRSwNPs and nasal mucosa from healthy controls." (PMID 33603773, 2021). "We found that ALOX5AP, BCL2A1, BTK, CYBB, NCF2, HCK, and HK3 were broadly expressed on both epithelial layer and stromal layer in nasal polyp tissues." (PMID 33603773, 2021). "The western blot results showed the expression level of ALOX5AP, BTK, CYBB, NCF2, HCK, and HK3 in CRSwNP was significantly increased in nasal polyps compared to control subjects." (PMID 33603773, 2021). "Our study has proved the increased expression of ALOX5AP, BCL2A1, BTK, CYBB, NCF2, HCK, and HK3 by mRNA and protein levels in nasal polyps." (PMID 33603773, 2021). "hsa-mir-27a-3p may promote the occurrence of inflammation and the formation of nasal polyps by regulating the expression of AZGP1, NCF2, CCL13, MUC7, PIP, and STATH." (PMID 36059464, 2022). "Moreover, the immunohistochemistry stain results also demonstrated that the protein level of ALOX5AP, BCL2A1, BTK, CYBB, NCF2, HCK, and HK3 were significantly increased in nasal polyps compared to control subjects." (PMID 33603773, 2021).
non-alcoholic fatty liver disease (2 papers, 2023 to 2024). "Moreover, some scholars have found that NCF2 may be a key molecule in patients with nonalcoholic fatty liver disease complicated with AF, and the expression of NCF2 is significantly upregulated in patients with AF." (PMID 36863715, 2023).
pulmonary TB (2 papers, 2023 to 2024). "Of those, only one (mouse Ncf2 in Dots1 on chromosome 1) has a human homologue where a single SNP (G nucleotide in human NCF2 rs10911362) may provide a protective effect because this SNP was associated with a lower odds ratio for pulmonary TB in humans." (PMID 38861581, 2024).
staphylococcus aureus infection (2 papers, 2021 to 2023). An infectious process in which the bacteria Staphylococcus aureus is present. "High expression of NCF2 was associated with detection of biotic stimulus (BP category), MHC protein complex (CC category), pattern recognition receptor activity (MF category), and Staphylococcus aureus infection (KEGG category)." (PMID 34708124, 2021).
acute myeloid leukemia (1 paper, 2023). Acute myeloid leukemia (AML) is a group of neoplasms arising from precursor cells committed to the myeloid cell-line differentiation. "Recently, there is emerging evidence that high expression of NCF2 is associated with poor prognosis in patients suffering from acute myeloid leukemia." (PMID 37775746, 2023).
aging (1 paper, 2024). A developmental process that is a deterioration and loss of function over time. "This suggests that NCF2, as an important regulator in the immune system, has great study potential for CVDs and aging or aging-related diseases." (PMID 38649851, 2024).
alopecia (1 paper, 2025). Hair loss usually from the scalp. "S100A8 can promote ferroptosis through the NCF2/NOX2 pathway, thereby promoting cyclophosphamide-induced alopecia." (PMID 41035016, 2025).
anemia (1 paper, 2025). A reduction in the number of red blood cells, the amount of hemoglobin, and/or the volume of packed red blood cells. "Ncf2 indirectly promotes osteoclast differentiation, and mutations in Ncf2 or Ncf1 are correlated with chronic granulomatosis (CGD), a genetic disorder often accompanied by anemia." (PMID 40574855, 2025).
Arthritis (1 paper, 2017). Inflammation of a joint. "Our gene-disease association study supports the theory that NCF1 and NCF2 are associated with some immunological diseases including arthritis and granulomatous disease." (PMID 27878450, 2017).
Cirrhosis (1 paper, 2023). A chronic disorder of the liver in which liver tissue becomes scarred and is partially replaced by regenerative nodules and fibrotic tissue resulting in loss of liver function. "Then, we implemented univariate Cox regression analysis, combining NCF2 expression level with some clinicopathological information we had got, such as age, gender, tumor size, differentiation, cirrhosis, lymphovascular space invasion (LVSI), capsular invasion (CapI), and necrosis." (PMID 36680322, 2023).
colorectal adenocarcinoma (1 paper, 2021). The most common type of colorectal carcinoma. "There was a high level of mRNA expression of NCF2 in patients with colorectal adenocarcinoma compared with normal tissue." (PMID 33506057, 2021).
COVID-19 (1 paper, 2023). A disease caused by infection with severe acute respiratory syndrome coronavirus 2. "In particular, we found an association between plasma proteins elevated in severe COVID-19, such as HGF, AREG, CKAP4, S100A12, NCF2, ITGB6, and a subpopulation of monocytes with lower expression of CD86 and HLA-DR, which are characteristics of myeloid-derived suppressor-like cells." (PMID 36829233, 2023). "Among these proteins, KRT19, TOP2B, AREG, HGF, CKAP4, ITGB6, and NCF2 had a higher expression (> twofold) in plasma samples of severe compared to moderate COVID-19 patients, whereas CLEC4C and LTA were among the few proteins that were expressed at lower levels in severe patients." (PMID 36829233, 2023).
Friedreich ataxia (1 paper, 2016). An inherited condition that affects the nervous system and causes movement problems. "We suggest that in addition to frataxin expression, blood lymphoblast levels of NCF2 and PDLIM1 could be useful biomarkers for disease progression and drug effect in future clinical trials of Friedreich’s ataxia." (PMID 27078885, 2016).
hyperlipidemia (1 paper, 2019). "All these data demonstrate that NCF2, MYO1F, S1PR4, and FCN1 in PBMC combination with sex and hyperlipidemia could be diagnostic biomarkers for obstructive CAD." (PMID 31245869, 2019). "Subsequent analysis of the diagnostic value of these genes in obstructive CAD further confirmed that NCF2, MYO1F, S1PR4, and FCN1 together with risk factors, gender, and hyperlipidemia, could improve the diagnostic accuracy of distinguishing obstructive CAD from free of obstructive CAD." (PMID 31245869, 2019).
Insulin resistance (1 paper, 2019). Increased resistance towards insulin, that is, diminished effectiveness of insulin in reducing blood glucose levels.
ischemic disease (1 paper, 2023). Lack of blood supply to an area of the body, resulting in impairment of tissue oxygenation. "Currently, studies on the co-effects of NCF2 and CYBB on ROS are mainly seen in autoimmune, infectious, and ischemic diseases." (PMID 36671813, 2023).
liver cancer (1 paper, 2022). An epithelial or non-epithelial malignant neoplasm that arises from the liver. "Downregulated expression of T cell-related genes including NCF2 and HTAR3 indicated the poor prognosis of liver cancer." (PMID 34980144, 2022).
lung carcinoma (1 paper, 2023). "In lung cancer, the single nucleotide polymorphism of NCF2 was related to the prognosis." (PMID 36680322, 2023).